MAP3K11 (mitogen-activated protein kinase kinase kinase 11)
Description:
Activates the JUN N-terminal pathway. Required for serum-stimulated cell proliferation and for mitogen and cytokine activation of MAPK14 (p38), MAPK3 (ERK) and MAPK8 (JNK1) through phosphorylation and activation of MAP2K4/MKK4 and MAP2K7/MKK7. Plays a role in mitogen-stimulated phosphorylation and activation of BRAF, but does not phosphorylate BRAF directly. Influences microtubule organization during the cell cycle.
Synonyms: MLK3; PTK1; SPRK; MEKK11; MLK-3
Tractability: Small molecule: a drug acting on it is in phase 2 or 3 trials; a high-quality ligand is known; it belongs to a druggable protein family. PROTAC: it is named in the literature on targeted protein degradation; ubiquitination databases record sites on it; its protein half-life has been measured; a small molecule that binds it is known.
Target class: TKL protein kinase group; Protein Kinase; Enzyme; TKL protein kinase MLK family; Kinase; TKL protein kinase MLK subfamily
Chemical probes: PD134191, URMC-099
Gene: Protein-coding gene on chromosome 11 (65,597,755 to 65,615,382, reverse strand). Ensembl gene ENSG00000173327.
Subcellular location: Cytoplasm, cytoskeleton, microtubule organizing center, centrosome
Subcellular location (Human Protein Atlas): Centriolar satellite; Cytosol
Pathways (Reactome):
Signal Transduction: CDC42 GTPase cycle; RAF activation; RHOG GTPase cycle; RHOV GTPase cycle
Disease: Paradoxical activation of RAF signaling by kinase inactive BRAF; Signaling by moderate kinase activity BRAF mutants; Signaling downstream of RAS mutants
Gene Ontology:
Molecular function: identical protein binding; JUN kinase kinase kinase activity; MAP kinase kinase kinase activity; mitogen-activated protein kinase kinase kinase binding; protein binding; protein homodimerization activity; protein serine/threonine kinase activity; protein kinase activity; ATP binding; mitogen-activated protein kinase kinase binding; protein serine kinase activity; small GTPase binding
Biological process: cell cycle G1/S phase transition; JNK cascade; MAPK cascade; microtubule-based process; positive regulation of JNK cascade; protein phosphorylation; positive regulation of apoptotic process; positive regulation of neuron apoptotic process
Cellular component: centriolar satellite; centrosome; cytosol; membrane; microtubule; cytoplasm
Genetic constraint (gnomAD): Loss-of-function variants: 46 observed, 74.41 expected, observed/expected ratio (o/e) 0.62, 90% interval 0.49 to 0.79. The upper end of that interval is the gene's LOEUF score, 0.79, which puts it in group 3 of 6, group 1 being the genes least tolerant of losing a copy. Missense variants: 1,049 observed, 1,096.3 expected, observed/expected ratio (o/e) 0.96, 90% interval 0.91 to 1.01. Synonymous variants: 523 observed, 464.74 expected, observed/expected ratio (o/e) 1.13, 90% interval 1.05 to 1.21.
Homologues: Orthologues: chimpanzee MAP3K11 (99% identical), macaque MAP3K11 (98% identical), pig MAP3K11 (95% identical), mouse Map3k11 (95% identical), rat Map3k11 (94% identical), dog MAP3K11 (94% identical), rabbit MAP3K11 (94% identical), guinea pig MAP3K11 (94% identical), zebrafish MAP3K11 (50% identical). Paralogues in human: MAP3K9 (50% identical), MAP3K10 (48% identical), MAP3K21 (47% identical), MAP3K12 (25% identical), MAP3K13 (24% identical), MAP3K20 (16% identical), BRAF (15% identical), RAF1 (15% identical), TNNI3K (15% identical), ARAF (14% identical), TESK1 (13% identical), TESK2 (13% identical), and 11 more.